CD44 (CD44 molecule (IN blood group))
Diseases named in the same sentence as CD44 in open-access papers (continued):
Sharing a sentence is not in itself a finding about the gene and the disease.
breast carcinoma (continued). "Although these studies suggest that CD44 cooperates with MMPs to regulate cell invasion, the relation of HA-induced CD44 signaling to the regulation of protease expression and activity in invasive breast cancer cells is poorly defined." (PMID 22621373, 2012). "Here we have established the role of HIF-1α in regulating CD44 in MDA-MB-231 and SUM-149 breast cancer cells, and two of its variant isoforms in MDA-MB-231 breast cancer cells." (PMID 22937154, 2012). "CD44 has also been identified as a marker of stem-like breast cancer cells, although its functional role in this phenotype is not clearly defined." (PMID 22937154, 2012). "ALDEFLUOR-positive CD44+CD24− Lin− breast cancer cells are a small and highly tumorigenic population, putatively enriched with stem cells." (PMID 22253899, 2012). "Several studies have shown an association between CD44+/CD24- cells and the metastasis of basal-like breast cancers." (PMID 22762532, 2012). "Here, we identify a novel cis-element of the CD44 directs gene expression in breast cancer cells in a cell type specific manner." (PMID 23226410, 2012). "In 2003, Michael Clarke's group first identified a CD44+, CD24lo, ESA+ and lineage- subpopulation of human breast cancer cells, which can initiate tumors in immune-deficient NOD/SCID mice." (PMID 23554768, 2012). "Quantification of CD44+/CD24− cell population within each of the 56 breast cancer cases was performed through manual counting of the CD44+/CD24− (green) cells in 10 merged images of representative areas." (PMID 23028444, 2012). "In a similar study, paclitaxel treated CD24−/CD44+ breast cancer cells were more resistant to cytotoxic drug treatment compared to the total population." (PMID 23042145, 2012). "Positive immunostaining for CD44 in breast carcinomas was consistently present on the cell membrane of tumour cells and in infiltrating lymphocytes; the latter was therefore selected as an internal positive control." (PMID 23028444, 2012). "In this study, we examined the mechanism of tamoxifen resistance of CD44+CD24–/low breast cancer stem cells in vitro." (PMID 23554768, 2012). "As researchers are able to isolate ESA+ CD44+CD24-/low LIN- cells from breast cancer tissues, more and more studies on BCSCs have appeared, particularly on CD44+CD24-/low cell’s clinical correlation." (PMID 23046710, 2012). "CD44 expression was assessed in a breast cancer tissue microarray composed of tissue cores extracted from a total of 141 patients, representing all molecular subtypes of the disease." (PMID 22621373, 2012). "More recently, a combinatorial therapy with conventional chemotherapeutic agent and the anti-diabetic drug metformin has been shown to efficiently eliminate drug-resistant CD44+/CD24− cancer stem/progenitor cells in breast cancers." (PMID 24977105, 2012). "In breast cancer, gene silencing p90RSK resulted in decreased number of tumor initiating cell phenotype represented by changes in surface marker such as CD44 and decreased ability to form mammosphere." (PMID 23216670, 2012). "Several in vitro and in vivo studies indicate that the CD44+/CD24− fraction of breast cancer cells has tumour-initiating properties." (PMID 23028444, 2012). "CD44 protein expression levels in breast cancer tissues of 15 patients carrying the CC genotype were significantly lower than that in 12 patients carrying the CT or 4 patients carrying TT genotype (Kruskal Wallis Test: P = 0.003)." (PMID 22788972, 2012). "Using these methods, we showed that the breast carcinoma cells displayed four distinct sub-populations based on the expression pattern of CD44 and CD24." (PMID 23028444, 2012). "In humans, an increase in the proportion of CD44+ CD24− breast cancer cells has been observed after neoadjuvant chemotherapy, indicating likely CSC therapy resistance in vivo." (PMID 22295241, 2012). "The data collectively identified, for the first time, HIF-1α as a regulator of CD44 expression in breast cancer cells and tumors." (PMID 22937154, 2012).
breast carcinoma (continued). "Six1 levels are enriched in the CD24low/CD44+ TIC population in human luminal breast cancers xenografted through mice, and in tumorsphere cultures in MCF7 and T47D luminal breast cancer cells." (PMID 22765220, 2012). "Confocal analysis of fluorescence-labelled samples obtained at surgery will likely allow for the stratification of breast cancer patients into two groups with substantially different relapse rates on the basis of CD44+/CD24− cell percentage." (PMID 23028444, 2012). "In this study, we now add a further dimension to our understanding of CD44-promoted invasion of breast cancer." (PMID 22621373, 2012). "Our siRNA data implicates CD44 as an important mediator of erbB signalling in ER+ breast cancer cells with acquired tamoxifen resistance." (PMID 23039365, 2012). "Correspondingly, some studies have recently indicated qualitative and quantitative changes in CD44 expression in breast cancer." (PMID 22788972, 2012). "Later, this idea was confirmed when epithelial mesenchymal transition (EMT) traits were observed to correlate with the CD44+/CD24low/− stem cell phenotype in human breast cancer." (PMID 22400115, 2012). "Three to 5% MDA-MB-231-GFP, 10–11% MDA-MB-231BRMS-GFP, and 50–70% of MDA-MB-468 human breast cancer cell parental populations were sorted into CD44-positive fractions." (PMID 23155468, 2012). "There are studies demonstrated that EMT phenotype is highest in the CD44+/CD24−/low breast cancer CSCs, and CSCs enriched from breast tumors and metastatic breast pleural effusions express markers similar to cells that have undergone an EMT." (PMID 22761812, 2012). "The induction of CD44 also was sufficient to promote the spontaneous metastasis of these noninvasive luminal breast cancer cells to the liver in vivo." (PMID 22621373, 2012). "CD44 is an important CSC marker in breast cancer cells, especially in epithelial-like breast cancer cells." (PMID 22134360, 2012). "Inbreast cancer, the undifferentiated CD44+CD24−/low antigenic statecommonly attributed to breast cancer subpopulations with cancer stem cell (CSC) properties is highlyenriched with EMT transcriptional factors and mesenchymal markers." (PMID 23307622, 2012). "Together, our findings suggest that CR1 has the potential to regulate CD44 expression in breast cancer and BCSCs via its interaction with AP-1 and NFκB factors." (PMID 23226410, 2012). "CD44 expression was determined with immunohistochemistry (IHC) analysis of a breast cancer tissue microarray (TMA)." (PMID 22621373, 2012). "Previously, we have defined a CD44+/CD24−/low mammosphere-forming tumorigenic 493-gene signature in breast cancer." (PMID 22879872, 2012). "In vitro, the CD44-hyaluronan interaction has been shown to mediate the attachment of metastatic breast cancer cells to human bone marrow endothelial cells." (PMID 22295241, 2012). "We now show that the breast cancer cells T47D, are capable of producing CD44+ cells with stem-like properties on exposure to IL-6, which suggests that IL-6 promotes the induction of CSCs." (PMID 22134360, 2012). "Upon isolation for breast cancer initiating CD44+CD24 −/low cells by employing magnetic activated cell sorting, we observed the kinetics of metformin-induced killing drastically varied among CSC and non-CSC subpopulations." (PMID 22565037, 2012). "NFκB proteins have also been shown to be up-regulated in breast cancer stem cells (BCSCs), and their expressions have been correlated to increased expression of tumor stem cell markers, including CD44." (PMID 23226410, 2012). "The combined expressions with CD44 associated with stem cell-like characteristics and CD24 related to differentiated epithelial features as prognostic markers for breast cancer however remains controversial." (PMID 23046710, 2012). "Until recently ALDH1 was considered as one of the potential markers for identifying breast cancer stem cells along with CD44+/CD24−/low." (PMID 22693526, 2012).
breast carcinoma (continued). "Recently, it has been reported that disseminated breast cancer cells in human bone marrow are largely CD44+/CD24-, corresponding to EMT CSCs." (PMID 22934288, 2012). "It has previously been reported that human breast cancer stem cells often have an EpCAM+CD44+CD24-/low phenotype." (PMID 23088371, 2012). "We have recently identified that mRNA for the cell surface protein, CD44, is upregulated in endocrine-resistant breast cancer cells." (PMID 23039365, 2012). "Breast cancer is the first human tumor for which a putative CSC subpopulation has been isolated as CD44+CD24−/low cells." (PMID 22134360, 2012). "Five tagSNPs of CD44 (rs10836347C>T, rs13347C>T, rs1425802A>G, rs11821102G>A, rs713330T>C) were selected and genotyped in 1,853 breast cancer patients and 1,992 healthy control subjects in Eastern and Southern populations." (PMID 22788972, 2012). "CD44 is also reported to enhance integrin-mediated adhesion and transendothelial migration of breast cancer cells." (PMID 23166660, 2012). "A number of cell surface markers have been used to sort for breast cancer cells with tumor-initiating capacity, including CD44, CD133, ALDH, CD90, and CD117 (KIT)." (PMID 22233382, 2012). "It is therefore important to investigate the proportion of CD44+CD24-/low breast cancer stem cells for the diagnosis of metastases in axillary nodes." (PMID 23046710, 2012). "A multivariate analysis indicated that the percentage of CD44+/CD24− cancer cells was an independent prognostic factor related to metastasis (p = 0.003), suggesting a significant clinical relevance of the CD44+/CD24− subclass of breast cancer cells." (PMID 23028444, 2012). "Representative data from our S2N and S2 cell lines also challenge the validity of the CD24−/CD44+ marker combination and EpCAM expression as tumorigenicity markers in breast cancer." (PMID 23042145, 2012). "Cells with stem cell characteristics have been prospectively isolated from breast cancer using CD44 and CD24 as markers, which are present on Hs578T and MDA-MB-231 cells." (PMID 22235336, 2012). "The capacity for CD44 to increase MT1-MMP expression and promote its localization within invadopodia would be consistent with the capacity of CD44 to induce breast cancer cell invasion." (PMID 22621373, 2012). "Herein, we provide evidence that the inflammatory cytokine, IL-6, is capable of generating CD44+ cells with stem-like properties through inducing EMT in the T47D breast cancer cells." (PMID 22134360, 2012). "In breast cancer, CD44+CD24−/low, aldehyde dehydrogenase (ALDH1), and CD133 have been considered as markers of CSCs." (PMID 23049880, 2012). "Consistent with an association with the most clinically aggressive tumors, in vitro studies have demonstrated the role of HA and CD44 in stimulating breast cancer cell migration and cell invasion." (PMID 22621373, 2012). "It is also reported that hypoxia enriches the CD44+/CD24- breast cancer stem-like cells and CD44+ murine mesenchymal stem cells." (PMID 22642602, 2012). "Although such consequence is contrasting with CD44+ cells in breast cancer, eventually it has shown only CD44+ cells possess greater clonogenic ability than CD44− cells." (PMID 22693526, 2012). "To further investigate the role of CD44 in breast cancer cells, we overexpressed CD44 in MCF7 cells which have barely-detectable endogenous levels of this protein (FiguresÂ 1 and 9A)." (PMID 23039365, 2012). "In summary, our results support the strong clinical relevance of the CD44+/CD24− subclass of breast cancer cells." (PMID 23028444, 2012). "Injection of CD44/Sca1+ cells from mammary tumors or lungs of MMT mice resulted in the formation of tumors, regardless of the donor age." (PMID 22277639, 2012). "Some previous comparative studies using paired human breast cancer tissue obtained before and after chemotherapy found that CD44+/CD24− or ALDH1+ tumour cells increased significantly after chemotherapy, which is in agreement with our results." (PMID 21559013, 2011).
breast carcinoma (continued). "To test this assumption, we isolated CD326(ESA)+/CD44+/CD24−or low cells not only from the breast cancer cell lines MCF7 and MDA-MB231 but also from primary cultures of human breast tumor cells." (PMID 21935375, 2011). "Silibinin, a natural drug extracted from common thistles, which inhibits CD44 promoter activity and expression, is known to have anti-tumor properties in breast cancer, non small cell lung cancer, and colorectal carcinoma." (PMID 21541039, 2011). "There was a clear inverse correlation between the intensity of CD44 expression and BRCA1 nuclear expression in this series of breast cancers, indicating that higher expression of BRCA1 was associated with lower CD44 expression (p=0.04)." (PMID 23508738, 2011). "In breast cancer, a subset of CD44+/CD24−/low/ESA+ cells has been identified with as few as 100 cells of these cells being able to form tumors in mice." (PMID 21935375, 2011). "Spheres grown from breast cancer samples or breast cancer cell lines, for example, were more tumorigenic than the bulk of the population, showed an enrichment in CD44+/CD24− and SP cells, and a higher resistance to radiation." (PMID 24212655, 2011). "We demonstrate that individual CD44 isoforms can be associated to different breast cancer subtypes and clinical markers such as HER2, ER and PgR, which suggests involvement of CD44 splice variants in specific oncogenic signaling pathways." (PMID 21957977, 2011). "Most notably, a subset of CD44+/CD24−/low cells isolated from breast cancers appear enriched in CIC because of the high potential tumorigenicity of these subsets." (PMID 21935375, 2011). "Previous studies showed that CD44 knockdown cells were more sensitive to doxorubicin than BCSCs, similar to breast cancer cells." (PMID 22152097, 2011). "Sheridan and co-workers (2006) discovered CD44+CD24−/low populations constituted a high proportion of the total cell population in basal or myoepithelial breast cancer cell lines." (PMID 24212798, 2011). "The phenomenon of reversal of differentiation was not only exhibited with the altered expression of CD44/CD24 surface markers during culture but was also noticed in altered expression of ABCG2 in breast cancer cells." (PMID 21935375, 2011). "Flow cytometry—Analysis of breast cancer stem cell markers including CD44, CD24, CD49f and aldehyde dehydrogenase 1 (ALDH1)." (PMID 24212798, 2011). "To verify results from the breast cancer cell lines, we performed similar studies on isolated CD44+/CD24−or low subsets from primary culture of benign breast tumor (patient A) and an invasive breast cancer cells (patient B)." (PMID 21935375, 2011). "The initial reports that only the CD44+CD24−/low subpopulation of human breast cancer cells contains BCSC have been challenged by subsequent studies." (PMID 21317983, 2011). "Of clinical significance, an immune response that induces the EMT-associated emergence of CSCs as CD8+T-cells can induce the dedifferentiation of breast cancer cells, resulting in the generation of CD44+/CD24− stem cell-like cells." (PMID 24212663, 2011). "CSCs within an epithelial malignancy were first described in breast cancer and found to display specific cell surface antigen expression (CD44+CD24low/-)." (PMID 21304978, 2011). "In breast carcinomas, these cells express the CD44+/CD24−/low mesenchymal immunophenotype on the cell surface." (PMID 22203527, 2011). "With these examples as precedent we assumed that selection of ESA+/CD44+/CD24− cells from breast cancer cell lines and from patient breast tissue would be enriched in stem-like CIC." (PMID 21935375, 2011). "In our studies both the breast cancer cell lines MDA-M-231 and MCF-7 and the primary culture of patient breast cancer cells demonstrated enhanced expression of phosphorylated ATM in the CD44+/CD24−or low subpopulation after radiation." (PMID 21935375, 2011).
breast carcinoma (continued). "The interest for CD44 was reinforced by the finding that tumorigenicity of breast cancer cells was limited to a putative CSC subpopulation with CD44+/CD24-/low expression." (PMID 21957977, 2011). "We characterised the putative CSC-rich breast cancer by assessing the relationship between CD44/CD24 or ALDH1 expression in pre-chemotherapy tissue and clinicopathologic parameters." (PMID 21559013, 2011). "When CD44, HA, and heparanase are highly expressed in breast cancer cells, they generate a microenvironment that facilitates tumor progression and invasion." (PMID 21749678, 2011). "CD44 is known to play a key role in the self-renewal of cancer stem cells in several cancer types including breast cancer, pancreatic cancer, and acute myeloid leukemia." (PMID 21915300, 2011). "The greatest portion of a CD44+/CD24− subset was found in the mesenchyme-like breast cancer cell line MDA-MB-231 and this cell line has previously been characterized as having a basal cell phenotype." (PMID 21935375, 2011). "We isolated a breast cancer cell population (CD44+CD24- cells) from primary cultures of malignant breast tumors." (PMID 22152097, 2011). "Using primary human breast cancer tissues, it has been demonstrated that the CD44+/CD24−/EpCAM+ population of cells can support tumor initiation with as few as 100 cells and have self-renewing, stem-like properties." (PMID 21957456, 2011). "The radiation resistance of the CD44+/CD24−/low subset was not only exhibited in breast cancer cell lines and primary culture of breast cancer cells but also in benign tumor cells." (PMID 21935375, 2011). "Breast cancer cell lines enriched for CD44+/CD24− markers express higher levels of pro-invasive genes and display higher invasive potential." (PMID 21347385, 2011). "Human breast cancer stem cells were initially isolated by high expression of CD44 and low expression of CD24." (PMID 24212780, 2011). "Nevertheless, since CD44 has been shown to be amplified and overexpressed in breast cancer, this implicates a functional role in tumor development and growth." (PMID 21957977, 2011). "When polyethylenimine (PEI) DNA particles are conjugated with HA they showed more specific targeting of breast cancer cells with high CD44 expression." (PMID 21541039, 2011). "Our study aims to investigate the prognostic impact of CD44+CD24-/low immunoexpression in breast cancer." (PMID 21824412, 2011). "MMP-9 mediates invasion of mammary carcinoma cells and invasion/angiogenesis of keratocyte tumours by binding to the hyaluronan receptor, CD44." (PMID 21283680, 2011). "For example, a subpopulation of breast cancer cells which highly expressed CD44, were characterized as TICs." (PMID 21731740, 2011). "Abraham and colleagues determined that 78% of breast cancer cases assessed contained a CD44+CD24−/low population constituting less than 10% of the total cell population." (PMID 24212798, 2011). "Breast cancer cell lines showed a heterogeneous expression pattern of the CD44 isoforms, which shifted considerably when cells were grown as mammospheres." (PMID 21957977, 2011). "In breast cancers CD44+/CD24−/low cells are predominately limited to triple negative breast cancer, a subgroup of basal-like tumors, and the presence of the CD44+/CD24−/low subset is correlated inversely with breast cancer patient survival." (PMID 21935375, 2011). "Genetic signatures that predict poorer prognosis for primary breast cancer patients have been examined by comparing the gene expression profiles of CD44+/CD24−/low cell populations with other populations." (PMID 21253528, 2011). "In breast cancer, CD44+ CD24−/low ESA+ (epithelial surface antigen, also known as EpCAM) cells were identified as CSCs in a number of solid malignancies." (PMID 24212663, 2011). "To confirm this, we initially isolated BCSCs from malignant breast tumors based on their CD44 and CD24 expression pattern." (PMID 22152097, 2011).